TSPAN8 (tetraspanin 8)
Diseases named in the same sentence as TSPAN8 in open-access papers (continued):
Sharing a sentence is not in itself a finding about the gene and the disease.
malignant glioma (3 papers, 2015 to 2024). A grade III or grade IV glioma arising from the central nervous system. "Tetraspanin 8 is thought to influence the migration of malignant glioma cells by forming a complex with α3 integrin and Rictor protein." (PMID 39031113, 2024). "Increased expression of tetraspanin 8 was detected in malignant gliomas compared with control tissues." (PMID 39031113, 2024). "Together, these results demonstrated over-expression of Tspan8 in human malignant glioma tissues and cell lines." (PMID 25761241, 2015). "In the current study, we studied the expression and the potential functions of tetraspanin 8 (Tspan8) in malignant gliomas." (PMID 25761241, 2015). "This study is set to test the expression and potential functions of tetraspanin 8 (Tspan8) in malignant gliomas." (PMID 25761241, 2015). "One important finding of this study is that Tspan8 was in the complex with α3 integrin in human malignant glioma tissues or cells." (PMID 25761241, 2015). "Targeting Tspan8-rictor-integrin α3 complex may provide a potential therapeutic intervention for malignant glioma." (PMID 25761241, 2015). "It is about 6–7 times more Tspan8 expression in malignant gliomas than that in normal tissues." (PMID 25761241, 2015). "Through Western blot, we examined the expression of Tspan8 in human malignant gliomas." (PMID 25761241, 2015). "Therefore, targeting Tspan8-rictor-integrin α3 complex may provide a potential therapeutic intervention for malignant glioma." (PMID 25761241, 2015).
metastatic disease (3 papers, 2011 to 2024). "Conversely, CD9, TSPAN6, and TSPAN8 were downregulated in the tumor compartment of metastatic tumor." (PMID 38255741, 2024). "On the other hand, CD9, TSPAN6, and TSPAN8 were downregulated in the tumor compartment of metastatic tumor." (PMID 38255741, 2024). "Vice versa, TSPAN8 upregulated in OC and grouped into C3 to C6 would be a possible therapeutic target to reduced metastatic disease previously demonstrated in a preclinical setting using TSPAN8‐blocking antibody." (PMID 33016563, 2021).
nasopharyngeal carcinoma (3 papers, 2020 to 2025). A carcinoma arising from the nasopharyngeal epithelium. "TSPAN8 is overexpressed in nasopharyngeal carcinoma (NPC) tissues, where it is poorly differentiated and highly-metastatic." (PMID 32138170, 2020). "Similarly, in nasopharyngeal carcinoma, TSPAN8 can facilitate cell migration, invasion, and proliferation through the Akt/MAPK pathway." (PMID 41146237, 2025).
Abdominal obesity (2 papers, 2015 to 2019). Excessive fat around the stomach and abdomen. "The T2D risk allele of rs7903146 in TCF7L2 specifically contributed to an increased risk for T2D combined with abdominal obesity (P = 3.77 × 10−2) and the T2D risk allele of rs7961581 in TSPAN8/LGR5 was related to an increased risk for T2D with elevated TG level (P = 4.61 × 10−2)." (PMID 26599349, 2015). "In CTRF+ individuals, mRNA levels of TSPAN8 associated with T2D family history (p < 0.01), of IGF2BP2 tv7 with serum glucose levels, while in the total group of controls, KCNQ1 tv1 levels reversely with BMI, central obesity, glucose and LDL (mg/dl) levels (p < 0.05)." (PMID 30728419, 2019).
asthma (2 papers, 2025). "For female-specific relationships, TSPAN8-asthma (beta in females = 0.84, q-value in females = 2.52E-04) and PZP-dementia (beta in females = 0.96, q-value in females = 0.040) pairs were identified." (PMID 40877285, 2025).
cervical cancer (2 papers, 2015 to 2022). A primary or metastatic malignant neoplasm involving the cervix. "Tetraspanin 8 (Tspan8), a tetraspanin that is uniquely expressed only in a small number of normal tissues, is also found over-expressed in several cancers including colon, liver, prostate, ovarian and cervical cancers." (PMID 25761241, 2015). "The results showed that PLCB4, FBLN5, TSPAN8, CST6, and SERPINB7 were highly expressed in cervical cancer tissues (p<0.05)." (PMID 36408178, 2022).
metastatic carcinoma (2 papers, 2011 to 2019). A carcinoma which has spread from the original site of growth to another anatomic site. "It is thought that TSPAN8 contributes to the cell motility of metastatic carcinoma cell lines, mostly through its association with α6β4 and CD151 following PMA treatment, whereas association with α3β1 and α6β1 promotes haematogenic spread of tumour cells." (PMID 21081927, 2011). "Because extracellular vesicles (EVs) play an important functional role in metastatic cancer progression 37, 38, 39, and Tspan8 has already been shown to function as a modulator of EV release and function 13, we examined the number of EVs in the blood of tumour‐bearing animals." (PMID 30982971, 2019). "Our observations are in line with previous studies showing that ectopic TSPAN8 expression in low-metastatic carcinoma cells did not confer any advantage for cell proliferation but led to a high metastatic potential." (PMID 21081927, 2011).
acne (1 paper, 2024). An inflammatory process of the sebaceous glands which is characterized by comedones, nodules, papules and/or pustules on the skin. "Novel acne susceptibility gene TSPAN8 is a member of the transmembrane 4 (tetraspanin) superfamily." (PMID 36922633, 2024). "We detected significant enrichment of TSPAN8, along with other novel genes (LGR5, ZNRF3, KREMEN1) and several known acne susceptibility genes, for the GO biological processes gene sets “GO negative regulation of response to stimulus” and “GO regulation of response to stress”." (PMID 36922633, 2024).
adenoma (1 paper, 2017). A neoplasm arising from the epithelium. "Therefore, we are currently evaluating an antibody designed for the recognition of murine TSPAN8 in ApcMin/+ mice that develop multiple adenomas in their small intestine and colon that advance to more tumors in old animals." (PMID 28423546, 2017).
breast adenocarcinoma (1 paper, 2023). "Interestingly, 14-3-3θ was recently reported to promote TSPAN8 translocation into the nucleus in MDA-MB-231 cells (human breast adenocarcinoma)." (PMID 37059365, 2023).
breast tumor (1 paper, 2019). "In addition, injection of lentivirus expressing TSPAN8-shRNA significantly reduced the PyMT-MMTV-induced breast tumor growth in mice." (PMID 31253779, 2019).
COVID-19 (1 paper, 2023). A disease caused by infection with severe acute respiratory syndrome coronavirus 2. "The conserved role of TSPAN8 for all SARS-CoV-2 VOCs imply that TSPAN8 is an attractive therapeutic target to limit COVID-19, which we explored with a TSPAN8-blocking antibody approach developed in the oncology field." (PMID 36827975, 2023). "In infected patients, TSPAN8 expression decreases in airway brushes of acute illness in patients caused by non-SARS-CoV-2 respiratory viruses, while airway brushes from COVID-19 patients revealed preservation of TSPAN8 levels, despite depletion in goblet cells." (PMID 36827975, 2023). "Pre-treatment of airway organoids with a blocking TSPAN8 antibody decreased SARS-CoV-2 infection levels in airway organoids, suggesting TSPAN8 as a therapeutic target for COVID-19." (PMID 36827975, 2023). "TSPAN8-blocking antibodies diminish SARS-CoV-2 infection and may spur novel avenues for COVID-19 therapy." (PMID 36827975, 2023). "In addition, in the lungs of two COVID-19 patients, we could detect cells that express ACE2 and TSPAN8 concomitantly." (PMID 36827975, 2023).
fungal infection (1 paper, 2019). "ARA6 was reported as accumulating at fungal infection sites and being partially co-localized with the homolog of mammalian exosome membrane protein CD63 in Arabidopsis namely TETRASPANIN 8 (TET8)." (PMID 31396242, 2019).
Hypertension (1 paper, 2022). The presence of chronic increased pressure in the systemic arterial system. "Interestingly, TSPAN8, which was suggested by our approach as a DM drug target, was also identified as a potential target for hypertension." (PMID 35213968, 2022).
liver disease (1 paper, 2013). "We found significant fold changes for SPINK1, LEF1, TSPAN8, SPP1, OR2I1P and PTGFRN comparing HH-HCC with HH-liver disease and normal liver (p<0.05, one-way Anova)." (PMID 23527199, 2013).
lung disease (1 paper, 2014). "Ramp2 [Receptor (calcitonin) activity modifying protein 2], Acaa2 (Acetyl-Coenzyme A acyltransferase 2), Mdh1 (Malate dehydrogenase 1, NAD), and Tspan8 (Tetraspanin 8) are enriched mRNAs in the lungs and are involved in lung disease." (PMID 25070658, 2014).
prostate tumor (1 paper, 2018). "Oncomine data analysis comparing transcript expression of DPP4, TSPAN8, and NES between prostate tumor tissues and normal tissues revealed inconsistent upregulation of these genes in the different datasets." (PMID 30100995, 2018).
psoriasis (1 paper, 2014). An autoimmune condition characterized by red, well-delineated plaques with silvery scales that are usually on the extensor surfaces and scalp. "33% of PP-decreased DEGs (291/885) were expressed more highly in fibroblasts than any other cell type, of which TSPAN8 and PAMR1 were among the most strongly repressed in psoriasis lesions." (PMID 24885462, 2014).
schizophrenia (1 paper, 2015). A major psychotic disorder characterized by abnormalities in the perception or expression of reality. "Previously, many candidate genes, including NRG1 (encoding neuregulin 1), AUTS2 (autism susceptibility candidate 2), TSPAN8 (Tetraspanin-8), ZNF804A (zinc-finger protein 804A), among others, have been identified that might confer risk for schizophrenia." (PMID 26016498, 2015).
stomach carcinomas (1 paper, 2017). "This corroborates with an extensive RNA-seq study where TSPAN8 mRNA was found highly expressed in cell lines from colon and stomach carcinomas." (PMID 28423546, 2017).
tubulovillous adenoma (1 paper, 2021). An epithelial neoplasm morphologically characterized by the presence of a villous and a tubular architectural pattern. "The subpopulations of CD151- and Tspan8-positive exosomes, the subpopulations of metalloproteinase at the surface of СD9-positive exosomes and the level of 20S proteasomes in plasma exosomes in 15 CPPs (tubulovillous adenomas) and 60 CRCPs were evaluated using flow cytometry and Western blotting." (PMID 33773551, 2021).
viral infections (1 paper, 2024). "Tetraspanin-8 has also been shown to act as a key component of the pro-inflammatory signaling cascade in cancer and viral infections due to its interaction with other proteins." (PMID 39035000, 2024).
tumor (99 papers, 2006 to 2025). "The M17 gene module comprises core genes including TIMP1, TFF2, ITM2A, SPINK1, and TSPAN8, intimately associated with tumor stemness maintenance and invasion-metastasis capacity." (PMID 41450464, 2025). "TSPAN8 is also abundant in tumor-derived exosomes and is able to associate with integrins, particularly α4 and β4 integrin chains, in the target cells." (PMID 38275818, 2024). "For instance, the humanized monoclonal antibody hT8Ab4 showed an anti-tumor effect in multiple cancers associated with the nuclear translocation of TSPAN8." (PMID 38275818, 2024). "Clinically, TSPAN8 expression levels were positively linked with tumor stage, size and axillary node metastasis and inversely correlated with the overall survival time in PDAC patients." (PMID 34163029, 2021). "High-expression levels of SOX9 and TSPAN8 were associated with tumor stage, dismal prognosis and poor survival in PDAC." (PMID 34163029, 2021). "As in other tumors such as pancreatic cancer and breast cancer, TSPAN8 is upregulated at both the mRNA and protein levels, and its level is associated with the potential of the tumor to metastasize." (PMID 34540692, 2021). "High expression of SOX9 and TSPAN8 has been associated with tumor stage, poor prognosis and poor patient survival in PDAC." (PMID 34163029, 2021). "Despite the central role of TSPAN8 in critical processes for tumor progression, the underlying molecular mechanisms of TSPAN8 expression upregulation remain poorly understood." (PMID 34163029, 2021). "The metastasis-promoting tetraspanin Tspan8 associates with integrins and proteases, which promotes a migratory phenotype and opens a path for tumor cell egress." (PMID 31485223, 2019). "On the contrary, CD151 and Tspan8 expression in tumor cells has been frequently associated with increased migration, proliferation and angiogenesis induction." (PMID 30769765, 2019). "TSPAN8 also promotes the proliferation and metastasis potential of tumors by inducing angiogenesis and cell migration, but the detailed molecular mechanisms underlying the role of TSPAN8 in promoting tumor progression and metastasis are unclear." (PMID 27270327, 2016). "Apart from CD151, the tetraspanin TSPAN8 (previously known as CO-029, TM4SF3) has been also associated with tumor progression." (PMID 24350713, 2013). "While accumulating evidence suggests that TSPAN8 plays a role in the biogenesis and functions of tumor-derived exosomes, the underlying mechanisms by which TSPAN8 regulates communications between cancer cells and their microenvironment of various cancer types need to be explored further." (PMID 38275818, 2024). "TSPAN8 expression levels were positively associated with tumor size." (PMID 34163029, 2021). "Neu tumor cells can be divided into Cluster 1 and Cluster 2, both expressing higher levels of genes associated with secretory alveolar differentiation such as Csn1s1, Lalba and Tspan8." (PMID 32840210, 2020). "Tetraspanin 8 (TSPAN8) has been implicated in a number of different tumours, but the underlying mechanisms remain unclear." (PMID 31253779, 2019). "Tspan8-associated α6β4 binding to the LN3321-rich BM promotes tumor cell migration." (PMID 31921628, 2019). "Albeit Tspan8 has been linked to formation of tumor exosomes and association of Tspan8 with integrins and cell adhesion molecules may facilitate cancer cell motility, the underlying molecular mechanism linking Tspan8 to cancer metastasis is still unclear." (PMID 36078095, 2022). "However, our studies also demonstrate that the transcription factor Fra-2 is able to control the expression of other adhesion molecules as well (L1-CAM, ICAM-1, CD44, ITGB4, and TSPAN8) and thus allows the tumour cells to adhere to the selectin-deficient endothelium via these adhesion molecules." (PMID 34693476, 2022). "However, the mechanisms underlying the role of TSPAN8 in the regulation of tumor progression remain largely unknown." (PMID 31253779, 2019).
tumor (continued). "The expression of tetraspanin 8 correlated positively with several clinicopathological features such as stage, status of lymph node invasion, and degree of tumor differentiation." (PMID 39031113, 2024). "Numerous studies have implied the potential of detecting TSPAN8 expression in circulating tumor cells or exosomes as a blood biomarker for cancer diagnosis, prognosis, and metastasis prediction." (PMID 38275818, 2024). "In line with this, there is a positive correlation between high TSPAN8 expression and clinicopathological characteristics of an aggressive tumor, including tumor differentiation, invasion depth, lymph node metastasis, and clinical stage." (PMID 38275818, 2024). "Some tetraspanins, such as TSPAN8 and CD151, have been associated with advanced tumor stage, metastasis, and poor clinical outcomes." (PMID 38255741, 2024). "The tetraspanin Tspan8, commonly upregulated in tumor cells, plays a crucial role in altering the molecular content of tumor-derived EVs." (PMID 39796048, 2024). "Tspan1, Tspan11, Tspan13, Tspan28, Tspan29, and Tspan30 have been identified as biomarkers for tumor diagnosis and prognosis, while Tspan8, Tspan24, and Tspan27 show potential as biomarkers." (PMID 38649381, 2024). "In a xenograft model, rats injected with Cd151 and Tspan8-knockdowned tumor cells survived significantly longer than animals with control tumor cell injection." (PMID 38954230, 2024). "Several monoclonal antibodies against TSPAN8 have been developed and showed a significant inhibition of tumor growth and metastasis in preclinical cancer models." (PMID 38275818, 2024). "For instance, CD151 and TSPAN8, which have been proposed as potential therapeutic targets for CC, were overexpressed in the tumor region of stage 4 primary CC tumors." (PMID 38255741, 2024). "The tetraspanins CD151 and TSPAN8 support metastatic tumor growth and metastatic niche formation in the lung and bone marrow." (PMID 38954230, 2024). "In another study, administration of lutetium‐radiolabeled [177Lu] anti‐tetraspanin 8 monoclonal antibodies DOTA‐Ts29.2 resulted in a significant reduction in tumor size compared to controls." (PMID 39031113, 2024). "This study found a correlation between the expression level of tetraspanin 8 and the degree of malignancy of the tumor." (PMID 39031113, 2024). "In recent years, several studies have investigated the pro-tumor role of Tspan8 in digestive system tumors." (PMID 38389703, 2024). "Remarkably, CAR-T cells specifically targeting TSPAN8 showed high efficacy, with complete tumor eradication in some cases." (PMID 38275818, 2024). "TSPAN8 protein was selected because TSPAN8 gene showed the highest expression among the differentially expressed genes in the tumor compartment of stage 4 primary CC tissues." (PMID 38255741, 2024). "AEG-1 (astrocyte elevated gene-1), which promotes tumor progression and metastasis, upregulates TSPAN8 transcription through the activation of the MEK/ERK signaling pathway." (PMID 38275818, 2024). "Among the first identified tetraspanins, Tspan8 promotes tumor progression and metastasis, presumably by stimulating angiogenesis and cell motility." (PMID 37835445, 2023). "In contrast to GSTM1, TSPAN8 was the only upregulated Black patient tumor specific gene that at high expression levels associated with an increase in the hazard ratio (1.81) and decrease overall survival by 7.5 months." (PMID 36812168, 2023). "In other terms, antibodies to human or mouse Tspan8, on human tumor cells or normal mouse intestinal tissues, respectively, inhibit specifically a functional effect of Tspan8 that results in the increase of ECE1 activity." (PMID 37835445, 2023). "CAR-T cells specific for TSPAN8 can significantly decrease the tumor burden in a subcutaneous xenograft model." (PMID 36941633, 2023).